IVL (involucrin)
Diseases named in the same sentence as IVL in open-access papers (continued):
Sharing a sentence is not in itself a finding about the gene and the disease.
cervical cancer (8 papers, 2012 to 2025). A primary or metastatic malignant neoplasm involving the cervix. "IVL and/or other keratinocyte differentiation associated genes (such as certain keratins and small prolin-rich proteins) are down-regulated in cervical cancer specimens compared to normal cervical samples." (PMID 22333115, 2012). "The TOP2A, AURKA and CCNA2 in cervical cancer were significantly increased, while IVL, KRT1, and IGFBP5 were significantly decreased, compared with normal tissues, which was consistent with the screening results." (PMID 39060960, 2024). "Another group also demonstrated that involucrin might be involved in breast cancer, cervical cancer, and oral cancer." (PMID 35054979, 2022). "In the current study, miR-331-3p overexpression significantly down-regulates NRP2, E6 and E7 proteins, and sequentially up-regulates IVL expression, which may induce keratinocytic differentiation as identified by decreased p63 protein expression in human cervical cancer cells." (PMID 27548144, 2016). "TOP2A, AURKA and CCNA2 were overexpressed in cervical cancer, while IVL and IGFBP5 were low expression in cervical cancer." (PMID 39060960, 2024). "The expression of IVL was decreased in cervical cancer cell, but there was no statistical significance, which was consistent with the expression trend in GEO datasets." (PMID 39060960, 2024). "The expression of IVL was decreased in cervical cancer cell, but there was no statistical significance, which was consistent with its expression trend in GEO dataset." (PMID 39060960, 2024). "Involucrin function was perturbed in skin squamous cell carcinoma (SCC), and cervical cancer." (PMID 25419056, 2014). "Other functional biomarkers investigated in cervical cancer include markers of squamous differentiation cytokeratin (CK), cell cycle markers such as p21, p27, MCM5, cyclin A, cyclin E and cyclin D, and other molecules such as telomerase, involucrin, and survivin." (PMID 24260536, 2013). "However, interestingly, the TCGA database and GEPIA online website analysis showed that TOP2A, AURKA, CCNA2 and IVL were overexpressed and IGFBP5 was low expression in cervical cancer, and there was no statistical difference in the expression of KRT1 in cervical cancer tissue and normal tissue." (PMID 39060960, 2024).
breast carcinoma (5 papers, 1997 to 2023). "In the human breast cancer cell lines we studied, all of the Brk-positive cultures also expressed detectable levels of involucrin." (PMID 37445934, 2023). "We found that involucrin, a keratinocyte differentiation marker, was expressed in a high proportion (78%) of breast carcinoma samples and cell lines." (PMID 37445934, 2023). "This, combined with other studies reporting that around a quarter of breast tumours express involucrin, implies a possible link between differentiation processes and breast cancer." (PMID 37445934, 2023). "It is worth noting, however, that, of the eight breast cancer cell lines we examined, the ER-negative Sk-Br-3 had the highest level of involucrin expression which could be an indicator of responsiveness irrespective of ER status." (PMID 37445934, 2023). "As some breast carcinomas have previously been shown to express high levels of involucrin, a marker of keratinocyte differentiation, we hypothesised that some breast tumours may de-differentiate to a keratinocyte-derived ‘evolutionary history’." (PMID 37445934, 2023). "Therefore, the effect of culturing breast cancer cells in suspension on Brk and involucrin expression was examined." (PMID 37445934, 2023). "In addition, all the tumours that highly overexpressed involucrin also expressed Brk, suggesting that some Brk-positive breast cancers may have a more differentiated keratinocyte-like (or squamoid) phenotype at a cellular level." (PMID 37445934, 2023). "Breast cancer cell lines were analyzed for VDR, Brk and involucrin expression by Western blotting." (PMID 37445934, 2023). "1,25-dihydroxyvitamin D3, a known differentiation agent and potential anti-cancer agent, decreased proliferation in the breast cancer cell lines that expressed both involucrin and Brk, whereas the Brk/involucrin negative cell lines tested were less susceptible." (PMID 37445934, 2023).
head and neck squamous cell carcinoma (3 papers, 2004 to 2020). A squamous cell carcinoma that arises from any of the following anatomic sites: lip and oral cavity, nasal cavity, paranasal sinuses, pharynx, larynx, and salivary glands. "IVL was a specific and sensitive marker of cell differentiation, the expression of IVL in head and neck squamous cell carcinoma patients with or without lymph node metastasis was significantly different." (PMID 33240619, 2020).
Hyperkeratosis (3 papers, 2013 to 2023). Hyperkeratosis is a histopathological term defining a thickened stratum corneum and may be present in many different skin conditions, with many possible overlaps. "Conversely, inflammation response, e.g. the production of IL-1, was found to have a strong effect on the creation of hyperkeratosis, which included changes in keratin and involucrin levels." (PMID 24678259, 2013). "Moreover, mice deficient in INVOLUCRIN, ENVOPLAKIN, and PERIPLAKIN show barrier defects, decreased desquamation, and hyperkeratosis that is concomitant with decreased KLK activity." (PMID 27551807, 2016).
inflammatory skin disease (3 papers, 2012 to 2024). Inflammatory skin disorders covers a broad category that includes many conditions ranging in severity, from mild itching to grave medical health complications These disorders are common in people of all ages and races. "No other correlation was found among IVL, hBD-2, IVL mRNA, hBD-2 mRNA, TPP2 mRNA and PSMB8 mRNA, neither in the patients with inflammatory skin diseases nor in the control group." (PMID 39273140, 2024).
oral cancer (3 papers, 2022 to 2024). "An up-regulation of IVL after RNAi-based VIM depletion was found in malignantly transformed oral cancer cells." (PMID 39682709, 2024).
papilloma (3 papers, 2014 to 2022). A benign epithelial neoplasm that projects above the surrounding epithelial surface and consists of villous or arborescent outgrowths of fibrovascular stroma. "While the loss of iASPP increased the papilloma onset and burden, iASPP-KO papillomas showed higher expression of differentiation markers (e.g., involucrin), suggesting a more “benign” tumor phenotype." (PMID 36261000, 2022). "We observed a downregulation of envoplakin, periplakin, and involucrin in WT papillomas and SCCs, leading us to speculate that the increased risk of SCC conversion in EPI−/− papillomas may be linked to the lack of two desmosomal proteins." (PMID 24843010, 2014). "Of note, iASPP-KO papillomas showed increased numbers of cells strongly positive for differentiation markers keratin 1 (CK1) and involucrin." (PMID 36261000, 2022).
skin cancer (3 papers, 2014 to 2024). "In contrast, another mouse model deficient in envoplakin, periplakin, and involucrin (Epi−/− mice), three components of the epidermal barrier on which the cornified envelope assembles, have a defective epidermal barrier that is protective against skin cancer." (PMID 39625985, 2024). "Histologic analysis and staining for Involucrin, Cytokeratin-14 and β-Catenin revealed that these skin tumors were all malignant SCC." (PMID 25329316, 2014).
asthma (2 papers, 2015 to 2024). "The differentially expressed genes included those related to inflammation (CCL22, CXCL16, AREG, MMP12) involved in asthma pathophysiology, as well as genes associated with the skin barrier (IVL, CDSN, SPINK5, FLG)." (PMID 39451560, 2024).
cholesteatoma (2 papers, 2012 to 2015). A pathologic process characterized by the proliferation of keratinizing squamous epithelium resulting in the accumulation of keratin and cells in the middle ear and/or mastoid. "Previous data suggests an interaction between FLG and involucrin (IVL), a protein that creates a protective envelope around corneocytes, and increased IVL in cholesteatoma; we identified increased IVL in cholesteatoma matrix, but not at levels meeting detection threshold (1.97-fold increase)." (PMID 26608071, 2015).
dermatitis (2 papers, 2013 to 2020). An inflammatory process affecting the skin. "The effects of genistein and PEA were compared by measuring the expression of involucrin using western blot and immunohistochemistry in dermatitis-induced animal models." (PMID 32063982, 2020).
esophageal cancer (2 papers, 2014 to 2023). A primary or metastatic malignant neoplasm involving the esophagus. "C-Jun increased the promoter activities of cystatin A, involucrin, and SPRR3 in a dose-dependent manner, suggesting that c-Jun activates the promoters of these differentiation-associated genes in vivo in esophageal cancer cell line." (PMID 24796531, 2014). "Of the top 20 genes whose expression most correlated with ZNF750 expression in esophageal cancer, 10 were epidermal differentiation and keratinization-related genes, such as LYPD3, KRT6A, KRT16, and IVL." (PMID 37365152, 2023).
psoriasis vulgaris (2 papers, 2024 to 2025). Plaque psoriasis is the most common presentation of psoriasis. "Involucrin, a precursor protein that plays a role in stabilizing the cornified envelope (CE), is also upregulated in psoriasis vulgaris, where CE formation appears to be initiated prematurely, and involucrin remains the major constituent of the CE during maturation." (PMID 40243580, 2025).
skin squamous cell carcinoma (2 papers, 2014 to 2020). A carcinoma arising from the squamous cells of the epidermis. "A previous study showed that both EGFR small interfering RNA (siRNA) and EGFR inhibitors increase the expression of several differentiation markers, including keratin 1, keratin 10, and involucrin in primary human keratinocytes, intact epidermis, and skin squamous cell carcinomas." (PMID 33096942, 2020).
breast tumour (1 paper, 2023). "We investigated whether Brk and involucrin were co-expressed in breast tumours." (PMID 37445934, 2023).
chronic obstructive pulmonary disease (1 paper, 2025). A chronic and progressive lung disorder characterized by the loss of elasticity of the bronchial tree and the air sacs, destruction of the air sacs wall, thickening of the bronchial wall, and mucous accumulation in the bronchial tree. "In addition, a substantial increase in abundance of involucrin suggesting a plausible stratified squamous cell differentiation and increased cell lysis in the oral cavity of medwakh smokers akin to chronic obstructive pulmonary diseases (COPD)." (PMID 39819313, 2025).
colon adenocarcinoma (1 paper, 2015). "Human colon adenocarcinoma cells (Caco-2) were treated with the partially purified and freeze dried WSE from legume D and S aiming at investigating filaggrin (FLG) and involucrin (IVL) gene expressions through RT-PCR." (PMID 26494432, 2015).
contact dermatitis (1 paper, 2024). An inflammatory skin condition caused by direct contact between the skin and either an irritating substance or an allergen. "Bilateral ovariectomy in mice resulted in reduced skin barrier function, decreased skin recovery after acute disruption, increased irritant contact dermatitis, and downregulated epidermal proteins, filaggrin and involucrin." (PMID 38675137, 2024).
COVID-19 (1 paper, 2024). A disease caused by infection with severe acute respiratory syndrome coronavirus 2. "However, in this study, an upregulation of other pro-inflammatory cytokines, including CRNN, IL1A, IL23A, IVL, and S100A7, was associated with severe COVID-19." (PMID 38375062, 2024).
dysplasia (1 paper, 2022). A usually neoplastic transformation of the cell, associated with altered architectural tissue patterns. "The results showed reduced or loss of Involucrin in the dysplasia and OSCC lines as opposed to normal control cells, the finding agreed with a previous report and suggesting that neoplastic transformation causes attenuation of the differentiation markers." (PMID 35000271, 2022).
folliculitis (1 paper, 2024). Inflammation of the hair follicles. "Folliculitis observed with tapinarof can be associated with increased follicular cornification with subsequent plugging, resulting from the upregulation of stratum corneum components, including filaggrin, hornerin, and involucrin." (PMID 39150292, 2024).
hand eczema (1 paper, 2020). A form of contact dermatitis characterised by inflammation, redness and itching of the hands. "Another remarkable finding in our study was the upregulation of involucrin, which has not been described in hand eczema before, although sufficient studies are lacking." (PMID 32333380, 2020).
head and neck cancer (1 paper, 2017). A primary or metastatic malignant neoplasm affecting the head and neck. "In head and neck cancers, the inhibition of Gsk3β also reduced the expressions of stem cells markers such as Oct4, Sox2, and Nanog, but increased the levels of differentiation markers Calgranulin B and Involucrin in CD44high/ESAhigh cells fraction." (PMID 28076327, 2017).
Hyperglycemia (1 paper, 2015). An increased concentration of glucose in the blood. "Despite different cell growth patterns in response to glycemic changes in HNSCC cells, decreased involucrin protein expression was detected in HNSCC cells incubated in high-glucose medium in a time-course manner implying that hyperglycemia progressively impaired cell differentiation." (PMID 26337468, 2015).
intraepithelial neoplasia (1 paper, 2014). A precancerous neoplastic process that affects the squamous, glandular, or transitional cell epithelium without evidence of invasion. "The expression of cystatin A, involucrin and SPRR3 was remarkably decreased during the malignant transformation from normal epithelium to low-grade intraepithelial neoplasia (LGIN) or high-grade intraepithelial neoplasia (HGIN)." (PMID 24796531, 2014).
keloid (1 paper, 2018). An irregularly shaped, elevated mark on the skin caused by deposits of excessive amounts of collagen during wound healing. "In all the skin models described in this study, suprabasal involucrin was observed and was not just limited to the keloid constructs." (PMID 30370495, 2018). "Recently, we have shown that native keloids have increased epidermal thickness which was not related to hyperproliferation but may be related to abnormal involucrin expression." (PMID 30370495, 2018).
lichen planus (1 paper, 2010). A chronic, recurrent, pruritic inflammatory disorder of unknown etiology that affects the skin and mucus membranes.
lung carcinoma (1 paper, 2016). "This concurs with the study by Araya in which increased intensity of involucrin staining was reported in samples obtained during surgery for lung cancer in patients who also had stage 2 and 3 COPD, when compared to healthy organ donor lungs." (PMID 27228128, 2016).
nevus (1 paper, 2020). Nevus (or naevus, plural nevi or naevi, from nævus, Latin for "birthmark") is the medical term for sharply circumscribed[1] and chronic lesions of the skin or mucosa. "It suggested that significantly elevated FABP5, IVL, KRT6A, KRT15, KRT16, and TIMP2 proteins expressed in the CM than in the nevus tissues." (PMID 32934956, 2020). "Next, to validate differential expressions of six prognostic hub genes between CM tissues and nevus tissues, we performed IHC analysis and found significantly elevated FABP5, IVL, KRT6A, KRT15, KRT16, and TIMP2 protein expressions in the CM than in the nevus tissues." (PMID 32934956, 2020).
oral lichen planus (1 paper, 2010). Oral lichen planus is a chronic inflammatory oral condition of unknown aetiology characterized by T-cell-mediated chronic immune response and abnormal epithelial keratinization cycle. "Involucrin has also been identified as a diagnostic marker in oral lichenoid lesions based on observations of involucrin reactivity in the skin and in oral lichen planus." (PMID 20967260, 2010).
prurigo (1 paper, 2021). A name applied to several itchy skin eruptions of unknown cause. "Several interesting results, including increased BMI in the prurigo groups and the enhanced expression of the epidermal differentiation proteins loricrin and involucrin in all patient groups, could serve as the basis for future research, as the causes and implications of which are yet unclear." (PMID 34681107, 2021).
pterygium (1 paper, 2021). A wedge-shaped fibrovascular lesion arising from the bulbar conjunctiva and extending to the cornea. "An early microarray study identified SPRR3, SPRR1A, SPRR1B and IVL from the cornification subcategory as upregulated genes in pterygium." (PMID 34769520, 2021).
rosacea (1 paper, 2025). A chronic erythematous skin disorder that affects the face. "The epidermal barrier protein Involucrin has been reported to decrease in rosacea along with the diminished skin barrier." (PMID 41296102, 2025).
sebaceous tumors (1 paper, 2014). "In human sebaceous tumors, BLIMP1 was expressed by the most differentiated (IVL+ or weak FAS+) cells in the center of the neoplasm rather than in the periphery, where the most proliferative cells reside." (PMID 25358790, 2014).
skin infection (1 paper, 2023). An inflammatory process affecting the skin, caused by bacteria, viruses, parasites, or fungi. "The epidermal barrier has surprising functional redundancy that can compensate for loss of single protein components including loricrin or involucrin, and the NKO do not show any sign of flakyness, itching, or increased susceptibility to skin infections as would be expected with a barrier defect." (PMID 36772996, 2023).
spindle cell carcinomas (1 paper, 2022). "A low level of K5 was detected in KALLU+ cell–generated spindle cell carcinomas but not involucrin or loricrin." (PMID 36270982, 2022).
virus infection (1 paper, 2022). "Both Akata virus infection and AG876 virus infection decrease the expression levels of numerous different differentiation markers induced by methylcellulose suspension in uninfected NOKs, including K10, involucrin, GHRL3, ZNF750, KLF4, TGM1 and SPRR1A." (PMID 36190982, 2022).
vulvar carcinoma (1 paper, 2021). "Derived from vulvar carcinoma, A431 cells are not able to differentiate even in favorable growth conditions (cultivation in serum-free medium, low concentration of retinoic acid, high concentration of Ca2+), but they can still produce involucrin." (PMID 34834228, 2021).
xerosis (1 paper, 2011). "Additionally, dry skin or xerosis is associated with age-independent molecular changes including epidermal expression of basal and differentiation-related keratins as well as premature expression of the cornified envelope protein, involucrin." (PMID 21747841, 2011).